TLR3 (toll like receptor 3)
Diseases named in the same sentence as TLR3 in open-access papers (continued):
Sharing a sentence is not in itself a finding about the gene and the disease.
cancer (continued). "The ability to trigger type I IFNs has rendered TLR3 an attractive target in cancer therapy, but TLR3 has also been acknowledged as a mediator of pro-tumorigenic inflammation, which can drive cancer cell survival and proliferation." (PMID 28717003, 2017). "We furthered our investigation into a xenograft murine model and have observed a similar improvement in the anti-cancer activity of reovirus in TLR3 down regulated tumors." (PMID 28422714, 2017). "Recent evidences suggested that TLR3 worked as a possible therapeutic target in many types of cancers." (PMID 27336891, 2016). "To further study the role of TLR3 in cancer cell growth, we established 2 cell lines derived from CNE1 and SQ20B and stably transfected with a plasmid encoding a shRNA directed against TLR3, driven by a doxycyclin-inducible promoter (Tet-on system)." (PMID 27791989, 2016). "Targeting TLR3 through formulations of polyI:C is widely studied as an adjuvant in cancer immunotherapy." (PMID 27911948, 2016). "Taken together, our results suggest that EBERs are instrumental for launching a vicious cancer-promoting inflammatory response represented by TNFα via TLR3 in vritro and in vivo." (PMID 26172457, 2015). "This review provides an in-depth look into the concepts and mechanisms underlying CALR exposure, activation of the Toll-like receptor 3/IFN/CXCL10 axis, and the release of ATP and HMGB1 from dying cancer cells." (PMID 26486085, 2015). "At odds with their wild-type counterparts, Tlr3−/− and Ifnar1−/− murine cancer cells exposed to anthracyclines fail to vaccinate syngeneic mice against a subsequent injection of living cells of the same type." (PMID 25964783, 2015). "It has been reported that DV infection in human cancer cell lines is likely dependent on TLR-3 that mediates the subsequent secretion of IFN-α/β and viral replication 29, we thus introduced siRNAs of TLR-3 into cells to knockdown this molecule." (PMID 25754930, 2015). "Cancer cells responding to anthracyclines secrete type I IFNs as a consequence of TLR3 activation, and this is required for cell death to initiate adaptive immunity." (PMID 26300886, 2015). "Nevertheless, the role of TLR3 in cancer remains inconsistent, and its function in breast CSCs is unclear." (PMID 25257174, 2015). "TLR3 has attracted considerable attention from investigators in fields such as biochemistry, immunology, and medicine; however, we know little regarding the significance of TLR3 in human carcinoma cells." (PMID 25884709, 2015). "TLR3 activation on immune cells results in anti-cancer activities, where T cell-mediated responses are promoted." (PMID 24744758, 2014). "Previous studies have demonstrated TLR3 agonists to be promising adjuvants for cancer vaccines, especially in regards to their immunostimulatory properties." (PMID 24744758, 2014). "In a randomized clinical trial using poly (A:U) dsRNA, TLR3 agonist, chemotherapy was enhanced in patients with TLR3-positive cancers." (PMID 24904578, 2014). "Collectively, these data suggest three different hypothetic functioning modes for TLR3-dependent anti-cancer mechanism in PCa." (PMID 23551576, 2013). "There is increasing evidence that the toll-like receptor 3 (TLR3) is an interesting target for anti-cancer therapy." (PMID 20576118, 2010). "Samples of carcinomas with recurrence exhibited a significant increase in the mRNA levels of TLR3, TLR4 and TLR9." (PMID 21129170, 2010). "While TLR3 activation has been widely explored for its capacity to induce apoptosis or necroptosis and enhance antitumor immunity, accumulating evidence indicates that cancer cells can use TLR3 signaling to sustain proliferation, migration, stemness, and therapy resistance." (PMID 42278599, 2026).
cancer (continued). "Moreover, rescue with NLS-TLR3 led to a reduction of cancer cell apoptosis compared to rescue of TLR3 with NES-TLR3." (PMID 40675966, 2025). "When oligomerized, the miniprotein binders induce TLR3 signaling in cells, suggesting they may be useful components of vaccines or treatments for infectious disease or cancer." (PMID 39890776, 2025). "Generally, this means that most cancers occur due to the upregulation of the TLR3 gene." (PMID 40847033, 2025). "Interestingly, the patients with high TRG after neoadjuvant therapy had a higher percentage of cancer cells with TLR3 nuclear expression, accompanied with worse clinical outcomes and shortened survival." (PMID 40675966, 2025). "Our data suggest that cancer cell expression level of nuclear TLR3 may help the prediction of cancer patient prognosis and provide a prospective target for cancer treatment." (PMID 40675966, 2025). "In addition, immunohistochemistry analysis of cancer tissue clinical samples confirmed that TLR3 was highly expressed in the cancer cell nucleus of tumors after neoadjuvant chemotherapy." (PMID 40675966, 2025). "The mechanism of TLR3-mediated immune activation—through the induction of apoptosis, immune cell activation, and cytokine production—underpins the rationale for its use in cancer immunotherapy." (PMID 39988665, 2025). "Therefore, it is important to determine the roles of immunotherapeutic agents targeting TLR3 in cancer treatment." (PMID 40844548, 2025). "We next tested potential factors driving the nuclear translocation of TLR3 in cancer cells." (PMID 40675966, 2025). "Chemotherapeutic intervention induced marked elevation of total TLR3 expression in cancer cells, and the increased nuclear TLR3 may result from the increased expression level of total TLR3 and its translocation to the nucleus." (PMID 40675966, 2025). "Besides, increased levels of nucleus-localized TLR3 positively correlated with poor histological differentiation and vascular thrombosis of cancer patients, and negatively correlated with patients’ survival." (PMID 40675966, 2025). "Studies have shown that targeting TLR3 activation to induce apoptosis could be a potential therapeutic approach in cancer treatment." (PMID 40844548, 2025). "These agents function by stimulating TLR3, leading to enhanced expression of inflammatory genes and facilitating the infiltration of T cells into tumors, thus demonstrating significant potential in cancer treatment." (PMID 38732254, 2024). "Our findings show that activation of immune-related genes, such as interferon, which are known to belong to the antiviral pathway in CRC organoids, results in TLR3 activation in cancer cells in response to chemotherapy, highlighting the role of the TME in this innate immune response." (PMID 38921017, 2024). "In Mendelian randomization analyses, we observed little evidence for a causal effect of increased serum toll-like receptor 3 on any cancer risk." (PMID 38290287, 2024). "In addition to acting as an immunomodulator of TME, TLR3 can directly induce apoptosis of cancer cells." (PMID 39072334, 2024). "Thus, TL-532 represents a novel tool to decipher TLR3 function, with potential to improve clinical landscape to fight cancer." (PMID 37275475, 2023). "Pre-clinical and clinical trials based on the use of synthetic dsRNAs activating TLR3 are currently underway in adult cancers, but could also represent a promising therapeutic strategy in children and adolescents." (PMID 37414800, 2023). "Our results suggest pre-treatment with TLR3 agonists may improve STING-dependent cancer therapy outcomes." (PMID 36835537, 2023). "These authors demonstrated in a retrospective clinical study that systemic administration of Poly(A:U) was associated with a significant decrease relapse in TLR3-positives but not in TLR3-negative primary cancers." (PMID 37275475, 2023).
cancer (continued). "Moreover, TLR3 expression in cancer cells activated the CD103+ lung dendritic cell subset, which is specifically associated with the processing of antigens derived from apoptotic cells and their presentation to CD8 T cells." (PMID 37112730, 2023). "In the present study, we identified a new family of TLR3 agonists that activates myeloid cells, triggers the secretion of pro-inflammatory cytokines in both myeloid and cancer cells, and induces apoptosis specifically in cancer cells." (PMID 37275475, 2023). "However, TLR3 was also shown to function as a death receptor in cancer cells when engaged with dsRNA." (PMID 37414800, 2023). "The prognostic value of TLR3 expression has been reported in several cancers." (PMID 37414800, 2023). "Accordingly, TLR3 agonists are currently being tested in clinical trials for several adult cancers." (PMID 37414800, 2023). "However, the role and molecular mechanisms of TLR3 in cancer are quite complex, but there were significant correlations between the expression and SCNA of TLR3 and levels of immune cells infiltration of KIRC, LGG and PAAD." (PMID 36419829, 2022). "Collectively, TLR3 possessed cancer-promoting abilities in PAAD." (PMID 35000541, 2022). "Previous studies have reported that double-stranded RNA may be an important substance in cancer vaccines and may itself increase immune responses via TLR3 and RIG-Is." (PMID 36199130, 2022). "Indeed, aberrant RNA molecules can be released and detected by the endosomal pattern recognition receptor Toll-like receptor 3 (TLR3) on the cancer cell surface, thus stimulating the production of IFNs in an autocrine and paracrine fashion." (PMID 36010596, 2022). "Finally, given that the crucial roles of TLR3 in pyroptosis and cancer regulation, we investigated its biofunctions in PAAD through experiments in vitro." (PMID 35000541, 2022). "TLR3, 7, 8, and 9 are expressed in endosomal compartments, which can detect bacterial and viral nucleic acids and stimulate the production of Type I IFNs, initiating innate immunity against cancers." (PMID 35890342, 2022). "Recent studies have underscored the pivotal role of TLR3 in cancer metastasis." (PMID 35739335, 2022). "Then, we used GEPIA to study the expression levels of TLR3 in 33 cancer types." (PMID 36419829, 2022). "Additionally, a different intriguing study shows that HIV-infected cells can release exosomes with special RNA recognized by TLR3 for promoting cancer cell proliferation." (PMID 36389785, 2022). "Interestingly, another study found that activation of TLR3 prior to metastasis inhibited migration of cancer cells, while its activation during metastasis enhanced their migration." (PMID 35884895, 2022). "These two different pathways may be the basis of the different outcomes of TLR3 activation in cancer cells." (PMID 33986756, 2021). "Toll-like receptor 3 (TLR3) acts as a death receptor in several cancer cell lines." (PMID 34822366, 2021). "The abnormal expression of TLR3 has been reported on various of cancer tissues." (PMID 34094905, 2021). "TLR3, which mediates antiviral responses by recognizing double-stranded RNA (dsRNA), represents a valuable adjuvant that induces a Th1-type of response, adapted to fight cancer." (PMID 34572013, 2021). "Importantly, TLR3 has also been suggested as a potential biomarker in other types of cancers and diseases." (PMID 34531911, 2021). "TLR3 is expressed in certain types of cancers that are often related to viral infection." (PMID 33986756, 2021). "Therefore, careful studies of individual cancer types regarding the effects induced by cell-surface expressed TLR3 are indispensable to determine either beneficial or detrimental outcomes." (PMID 33597952, 2020).
cancer (continued). "Activation of TLR3-TRIF pathway also induces apoptosis in cancer cells." (PMID 33633744, 2020). "In addition, TLR3 activation has been reported to mediate apoptosis in several cancer histotypes, primarily through an extrinsic pathway." (PMID 32093313, 2020). "Moreover, we showed that TLR3 expression on cancer cells contributes to activate the CD103+ lung dendritic cell subset, that is specifically associated with processing of antigens derived from apoptotic cells and their presentation to CD8+ T lymphocytes." (PMID 32093313, 2020). "However, TLR3 activation has been reported to induce cancer progression as well by the induction of VEGF, MMP9 and uPAR via Myc- and MAPK signaling." (PMID 33679703, 2020). "Although TLR3 promoted invasiveness of IECs in the discussed work, the dsRNA stimulation may entail apoptosis and reduce cell viability in various cancer types in a TLR3-dependent manner." (PMID 33597952, 2020). "Indeed, ERE RNAs (including LINES, SINEs, and LTRs) were found to be enriched in exosomes released by cancer cells, to activate TLR3 and RLRs and to trigger IFN signaling." (PMID 31076589, 2019). "Consistent with this speculation, TLR3 was reported to induce apoptosis in cancer cells that were treated in vitro with a synthetic TLR3 agonist." (PMID 31582772, 2019). "Moreover, numerous cancers are characterized by upregulation of TLR3, a receptor for poly(I:C), and in most of these cancers this TLR3 positivity is predictive of a favorable outcome if poly(I:C) is used as an immune therapeutic." (PMID 30992466, 2019). "In addition to promote cytokines secretion, Toll-like receptor 3 (TLR3) activation on cancer cells has been reported to mediate apoptosis in several cancer histotypes, primarily through an extrinsic pathway." (PMID 31582772, 2019). "In our study, we focused on TLR3 agonist Riboxxol, a 50 bp dsRNA, for immunotherapy of cancer." (PMID 30824859, 2019). "Recently, a crucial role of TLR-3 has been suggested in cancer." (PMID 30072995, 2018). "Interestingly, we found that even after repeated injections of Poly(I:C) in the mice, TLR3 expression in xenograft cancer cells was maintained." (PMID 30158588, 2018). "Furthermore, the TLR3/dsRNA inhibitor reduced ERK1/2 phosphorylation in HSC3 cancer cells treated with J1.1 cell exosomes." (PMID 30389917, 2018). "HIV-infected J1.1 cell exosomes and synthetic HIV TAR RNA induced significant expression of TLR3-responsive ISGs IFIT1 and IFNB1 in SCC9 and HSC3 cells, suggesting that TAR RNA-bearing exosomes from HIV-1-infected T cells would signal through TLR3 in cancer cells." (PMID 30389917, 2018). "Additionally, several cancer cells have been shown to express TLR3 at various levels, including hepatocellular carcinoma, breast cancer, and neuroblastoma." (PMID 30740111, 2018). "TLR3-mediated apoptosis in human cancer cells involves a signalosome called ripoptosome." (PMID 30158588, 2018). "Poly(I:C) induces apoptosis in some cancer cells in a TLR3-dependent manner." (PMID 28717003, 2017). "We conclude that altered TLR3 expression and localization may have implications for cancer progression." (PMID 28717003, 2017). "Finally, Liu and colleagues detailed an investigation into the interaction between cancer-derived exosomes and Toll-like receptor 3 (TLR) in establishing a pre-metastatic niche in lung cancer." (PMID 28796150, 2017). "Importantly, a novel inhibitor of pathologic TLR3 signaling, phenylmethimazole (C10), has the ability to block IL-6 production, as well as decrease viability/growth and migration in these same cancers." (PMID 29371911, 2017). "We hypothesized that the effect of C10 on viability/growth and migration of these cancers was related to its suppressive effect on TLR3 signaling which led to the inhibition of TLR-mediated STAT3 and Wnt5a signaling." (PMID 29371911, 2017).
cancer (continued). "Our group has identified phenylmethimazole (C10), an inhibitor of pathologic TLR3 signaling/expression, and shown that C10, by virtue of inhibiting the TLR3/Wnt5a pathway is significantly efficacious in in-vitro and in-vivo models of different cancers and auto-immune diseases." (PMID 29371911, 2017). "Activation of TLR3 signaling by its agonists can induce apoptosis in human cancer cells." (PMID 27533082, 2016). "Genetically knocking out TLR3 or the IFN-α/β receptor (IFNAR) in cancer cells ablated this protection, an effect that could be reversed by administering recombinant type I IFN or CXCL10 in the respective knockouts." (PMID 26486085, 2015). "The results of these studies suggest that monitoring biomarkers of TLR3 and type I IFN signaling may not only have prognostic/predictive relevance for cancer patients, but also inform on the risk for cancer development in healthy subjects." (PMID 26300886, 2015). "Regardless of the genetic model, no other TLR3 SNPs (rs3775290, rs3775291, and rs3775292) were found to be associated with cancer risks." (PMID 26063214, 2015). "On the other hand, it has been shown that TLR3 and IRF-3 were down-regulated in a subset of human PCa tissues and that TLR3-downregulation was associated with recurrence, suggesting a successful immune system escaping strategy for some advanced cancers." (PMID 25444175, 2015). "In summary, there are 10 types of cancer that have been evaluated in relation to TLR3 SNPs." (PMID 26063214, 2015). "The TLR3 rs5743312 polymorphism is located in intron 3, and no previous studies have shown any association between this polymorphism and cancer risk." (PMID 26063214, 2015). "Lipopolysaccharide, a TLR4 ligand, provides pro-survival signals to cancer cells, thereby inducing therapy resistance, whereas a synthetic double-stranded RNA (dsRNA) poly(I:C), a ligand for membrane-bound TLR3, shows direct antitumor effects on a variety of cancers." (PMID 25227113, 2014). "In addition, TLR3 was found to be involved in different cancers and was also reported to affect intestinal inflammation in a complex manner depending on the conditions, either protecting from inflammation or causing epithelial destruction." (PMID 25242873, 2014). "This two component RNA vaccine (mRNA to mediate antigen expression in situ and non-coding dsRNA to stimulate the innate immune system via TLR3) is efficacious in animal models of influenza and cancer, and has been shown to be safe and immunogenic as a cancer vaccine strategy in humans." (PMID 23914187, 2013). "The smallest region of overlap (region 4q35.1-4q35.2) encompasses the cancer associated genes TLR3, CDKN2AIP, ING2, CASP3 and SORBS2, none of which are thought to cause aberrant DNA methylation." (PMID 20444249, 2010). "Our study may open a new range of therapeutic applications for TLR3 agonists as a adjuvant of chemotherapy drugs in some certain cancers." (PMID 18199340, 2008). "Additionally, we demonstrate a discontinuous staining for TLR3 protein within epithelial glands of G1 carcinoma, comparable to the findings in secretory and menstrual phase of premenopausal women." (PMID 18775079, 2008). "Importantly, we discuss the key determinants governing TLR3 signaling output, including signaling complex composition; ligand origin and delivery; TLR3 subcellular localization; and cancer cell-intrinsic factors such as genetic, epigenetic, and metabolic states." (PMID 42278599, 2026). "Additionally, TLR3 activation mediates apoptosis via the extrinsic pathway in various cancer types." (PMID 40844548, 2025).